DPP4 (dipeptidyl peptidase 4)
Diseases named in the same sentence as DPP4 in open-access papers (continued):
Sharing a sentence is not in itself a finding about the gene and the disease.
Hypoglycemia (continued). "For instance, hypoglycemia is a common side effect of sulfonylureas, but is rare with GLP-1 agonists and DPP-4 inhibitors, which might mediate the relative risk difference when compared to sulfonylureas." (PMID 39429814, 2024). "The new generation of glucose-lowering medications, such as glucagon-like peptide 1 receptor agonists (GLP-1RA), dipeptidyl peptidase-4 (DPP-4) inhibitors and sodium-glucose cotransporter 2 (SGLT-2) inhibitors may pose a lower risk for hypoglycaemia." (PMID 39407915, 2024). "The combination of a DPP-4 inhibitor with insulin is particularly attractive because it does not significantly increase the risk of hypoglycemia, as the insulin secretagogue effect is glucose-dependent." (PMID 40066124, 2024). "Across the trials, different combinations of SGLT2 inhibitors, DPP-4 inhibitors, metformin, and insulin were administered to evaluate their impact on glycemic control, cardiovascular and renal outcomes, weight changes, and hypoglycemia risks." (PMID 39723311, 2024). "In this context, DPP4 inhibitors seem to be very good candidates as are not known to cause hypoglycemia or weight gain, no requirement of dose escalation and have a favorable anti-inflammatory and safety profiles." (PMID 37287751, 2023). "DPP-4 inhibitors are associated with a very low risk of hypoglycaemia and are not linked with weight gain, gastrointestinal symptoms or peripheral oedema." (PMID 37287751, 2023). "An antidiabetic class switch was performed in 9 (9%) patients, for example, from repaglinide to DPP-4 inhibitor or sulfonylurea plus DPP-4 inhibitor to metformin in case of hypoglycemia, and from GLP1 receptor agonist to long-acting insulin plus glinide in case of hyperglycemia." (PMID 37760514, 2023). "In general, if no contraindication exit, DPP-4 inhibitors are also recommended due to the few side effects and minimal risk of hypoglycemia." (PMID 37035300, 2023). "In addition, DPP-4 inhibitors and SGLT-2 inhibitors can complement each other with their different action mechanisms, and the risk of hypoglycemia is relatively low, which is expected to reduce side effects and increase the therapeutic effect." (PMID 37111730, 2023). "For example, dipeptidyl peptidase-4 (DPP-4) inhibitors and sodium-glucose co-transporter 2 (SGLT-2) inhibitors have a low risk of hypoglycaemia; in contrary, sulfonylureas and thiazolidinediones may cause weight gain." (PMID 35655228, 2022). "However, the action of GLP-1 is strictly regulated to prevent the development of hypoglycemia by rapid degradation and deactivation of the peptide by the action of an enzyme called dipeptidyl-peptidase-IV (DPP-4)." (PMID 33915871, 2021). "Moreover, when DPP-4 inhibitors block persistent glucagon oversecretion, glucagon responds normally to a drop in BG level and ameliorates hypoglycemia." (PMID 34203048, 2021). "DPP4 inhibitors added to basal insulin improve glycaemic control without increasing the risk of hypoglycaemia, even among hospitalised patients." (PMID 32405783, 2020). "We also selected the incidence of hypoglycemia as a safety index for DPP-4 inhibitors." (PMID 33224988, 2020). "DPP-4 inhibitor, which is one of the incretin-based therapies that increase the concentration of circulating GLP-1, has been frequently used for the treatment of T2D because of its relatively low risk of inducing hypoglycemia." (PMID 32121372, 2020). "Additionally, at that time of the database analysis, DPP-4 inhibitors were considered to increase hypoglycemia, as indicated in several reports of hypoglycemia with DPP-4 inhibitors in combination with SUs." (PMID 31695754, 2019). "Because DPP-4 inhibitors effectively lower postprandial glucose levels and decrease the probability of hypoglycemia, DPP4-inhibitors could harmonize the safety and action of insulin treatment." (PMID 30611254, 2019).
Hypoglycemia (continued). "Several clinical trials also showed a consistent reduction in HbA1c when DPP-4 inhibitors were added to basal insulin therapy, with no increased risk of hypoglycemia." (PMID 31366085, 2019). "In addition to metformin, glucagon-like peptide-1 (GLP-1) agonists, dipeptidyl peptidase-4 (DPP-4) inhibitors and sodium–glucose cotransporter 2 (SGLT-2) inhibitors are all excellent choices for people who are at risk of hypoglycemia." (PMID 29960591, 2018). "Newer anti-diabetic agents such as sodium glucose cotransporter 2 (SGLT2) inhibitors and dipeptidyl peptidase-4 (DPP4) inhibitors are very useful in that they rarely cause common adverse effects of other oral hypoglycemic agents, such as weight gain and hypoglycemia." (PMID 29535389, 2018). "According to one recent cost-effectiveness analysis, the addition of NPH insulin to metformin and sulfonylurea combination therapy is the most cost-effective strategy; however, the use of a DPP-4 inhibitor is potentially cost-effective when higher rates of hypoglycemia are assumed." (PMID 29713649, 2018). "We found that DPP-4 inhibition with linagliptin ameliorated cognitive impairment and hippocampal neurodegeneration, improved CBF, prevented hair loss, lessened body weight loss, and ameliorated hypoglycemia in klotho−/− mice." (PMID 29195509, 2017). "DPP4 inhibitors decrease serum glucose levels with fewer hypoglycemia events and less weight gain, which may be cardio-protective." (PMID 28542373, 2017). "DPP-4 inhibitors do not cause weight gain and a single administration is unlikely to induce hypoglycemia." (PMID 28490337, 2017). "Takentogether, it seems that the presence of hypoglycemia is not the main cause ofincreased risk of HHF among patients treated with DPP4 inhibitors." (PMID 27460913, 2016). "Therefore, DPP-4 inhibitors would be an attractive choice for oldest old patients for its lower rate of hypoglycemia and neutral weight effects." (PMID 27246619, 2016). "In contrast, the DPP-4 inhibitor sitagliptin has not been reported to cause hypoglycemia and its FDC does not need a titration period." (PMID 26986104, 2016). "Nowadays, there are new noninsulin agents, DPP-4 inhibitors in particular, which present a low risk of hypoglycemia and can be used in patients with DM2 with CKD." (PMID 27471550, 2016). "Incretin-based therapies, GLP-1 agonists, and DPP4 inhibitors offer optimal glucose-lowering effect without increasing the risk for hypoglycemia and weight gain." (PMID 27881129, 2016). "On the other hand, if DPP4 inhibitors are combined with premixed insulin preparations or bolus insulin, it is necessary to adjust the insulin dose, particularly that of bolus insulin, to avoid hypoglycemia." (PMID 25780477, 2015). "Since incretin hormones stimulate insulin secretion in a glucose-dependent manner, DPP-4 inhibitors improve hyperglycemia without an increase in risk of hypoglycemia and weight gain." (PMID 25816296, 2015). "Based on these characteristics of DPP-4 inhibitors, adding a DPP-4 inhibitor to insulin is expected to improve glycemic control without an increase in risk of hypoglycemia and weight gain." (PMID 25816296, 2015). "These favorable changes in GV without an excess risk of hypoglycemia by treatment with DPP-4 inhibitors are expected to result in improvement of CVD outcome." (PMID 25314300, 2014). "However, NMA revealed that there were differences between dapagliflozin and the other classes of treatment in terms of impact on weight (dapagliflozin compared to DPP-4 inhibitors) and incidence of hypoglycaemia (dapagliflozin compared to GLP-1 analogues)." (PMID 25006351, 2014). "Compared with glipizide, the DPP-4 inhibitor reduced the incidence of severe hypoglycemia in dialysis patients significantly (five of 64 participants vs. 0 of 64, respectively) but not in non-dialysis patients (six cases of 212 participants vs. three cases of 210 participants)." (PMID 25360775, 2014).
Hypoglycemia (continued). "These GLP-1 analogs have demonstrated an HbA1C-lowering effect that is superior to that of DPP-4 inhibitors without increase of hypoglycemia risk." (PMID 23564338, 2014). "Only two articles compared the effects of DPP-4 inhibitor and glipizide on hypoglycemia." (PMID 25360775, 2014). "The incidence of hypoglycemia was markedly greater in the linagliptin group only when linagliptin was administered with sulfonylurea, which is consistent with clinical findings for other DPP-4 inhibitors." (PMID 23570327, 2013). "Amongst patients receiving any type of monotherapy, insulin use was the only positive predictor of incident hypoglycaemia (OR 6.59; 95%CI 4.43-9.79) while the reduced rate with DPP-4 inhibitors was statistically only borderline significant (OR 0.52; 95%CI 0.26-1.03)." (PMID 23075070, 2012). "This may have masked hypoglycaemia rates seen with sulfonylureas as has been shown to be the case in combination with for example DPP-4 inhibitors." (PMID 23075070, 2012). "Use of the GLP-1R agonists and DPP-4 inhibitors also enable the clinician to minimize the risk of some of the complications commonly encountered when treating patients with T2DM, such as hypoglycemia and weight gain." (PMID 22390369, 2012). "Oral dual combination therapy (0.44; 0.36-0.54), combination use of metformin with glitazones (0.46; 0.28-0.83), metformin with DPP-4 inhibitors (0.34; 0.25-0.45) and any OAD with GLP-1 analogues (0.47; 0.30-0.74) were associated with a reduced rate of hypoglycaemia." (PMID 23075070, 2012). "Dipeptidyl peptidase-4 (DPP-4) enzyme inhibitors, are a class of oral anti-diabetic medications, that have been shown to achieve improved glycemic control by lowering HbA1C, without causing hypoglycemia." (PMID 39865301, 2025). "Importantly,DPP4 inhibitors do not reduce blood glucose under normoglycemic conditions,thereby minimising the risk of hypoglycemia and supporting their potential as a safe therapeutic strategy for CD-associated fibrosis." (PMID 41334589, 2025). "Moreover, if the patient is on a medication with no risk of hypoglycaemia (e.g., metformin, SGLT2i, or DPP-4 inhibitors), we propose adopting a flexible target of up to 6–6.5%." (PMID 40014274, 2025). "Among the various classes of oral antidiabetic medications, dipeptidyl peptidase-4 (DPP-4) inhibitors have gained recognition for their ability to enhance insulin secretion and suppress glucagon release in a manner dependent on glucose levels, which helps reduce the risk of hypoglycemia." (PMID 40733260, 2025). "For example, Dipeptidyl peptidase-4 (DPP-4) inhibitors are a recently developed class of antidiabetic pharmaceuticals that are garnering attention for their additional benefits, including enhanced pancreatic function, a reduced risk of hypoglycemia, and weight reduction." (PMID 40406485, 2025). "Hypoglycemia rates, for example, were not significantly different between the sitagliptin and placebo groups, aligning with the known lower risk of hypoglycemia associated with DPP-4 inhibitors." (PMID 39768866, 2024). "However, GLP-1 agonists also demonstrated a lower dementia risk compared to DPP-4 inhibitors, suggesting no or minimal influence from hypoglycemia." (PMID 39429814, 2024). "Additionally, DPP-4 inhibitors may help protect against hypoglycemia by influencing pancreatic cells." (PMID 40066124, 2024). "Therefore, the increase in intact GIP levels observed after inhibition of DPP4 may help maintain the counter-regulatory response of glucagon when glucose levels are controlled at hypoglycemia." (PMID 35630534, 2022). "Dipeptidyl peptidase-4 inhibitors (DPP-4i) and the glucagon-like peptide-1 receptor agonists (GLP-1 RAs) have become widely used in T2DM patients as a novel class of blood glucose–lowering drugs with improved weight loss, low risk for hypoglycemia, and reduction in glycated hemoglobin." (PMID 35847027, 2022). "Furthermore, DPP-4 inhibitors can improve both hyperglycemia and hypoglycemia." (PMID 34203048, 2021).
Hypoglycemia (continued). "DPP-4 inhibitors are no more efficient in lowering blood glucose concentrations and reducing HbA1c levels than the older molecules and they provide certain advantages such as an insignificant risk of hypoglycemia and a weight-neutral profile." (PMID 34068380, 2021). "Some drugs that can be administered despite low eGFR values are marred by side effects such as hypoglycemia with repaglinide, volume retention and risk of distal fractures with pioglitazone, or may impact negatively on CKD progression (e.g., dipeptidyl peptidase 4 inhibitors)." (PMID 32235471, 2020). "Dipeptidyl peptidase-4 (DPP-4) enzyme inhibitors, are a class of oral anti-diabetic medications, that have been shown to achieve improved glycemic control by lowering HbA1C, without causing hypoglycemia, and are weight neutral." (PMID 32493344, 2020). "Moreover, DPP-4 inhibitors have a lower incidence of adverse events, including hypoglycemia." (PMID 32317735, 2020). "Moreover, one patient developed hypoglycemia during treatment with a DPP-4 inhibitor alone." (PMID 30815039, 2019). "DPP-4 inhibitors are important oral antidiabetic agents that are placed as second-line therapy after metformin failure as insulinotropic agents that have no intrinsic hypoglycaemia risk and are body weight neutral." (PMID 31275246, 2019). "Therefore, there is a great interest in determining whether DPP-4 inhibitors play an important role in protecting against hypoglycemia-induced vascular damages." (PMID 28067320, 2017). "It increases the physiological concentration of glucagon like peptide GLP-1 and glucose dependent insulinotropic polypeptide (GIP) in body by inhibiting the enzyme dipeptidyl peptidase –IV (DPP-4) with well tolerated profile, no risk of weight gain and hypoglycemia." (PMID 28083033, 2016). "Current indications for DPP-4 inhibitors recommend its use in combination with other antidiabetic agents, in particular with metformin, as second and third line therapy, and even over other antidiabetic therapies, especially if the patient is experiencing an increased incidence of hypoglycaemia." (PMID 26075286, 2015). "DPP4 inhibition has not caused hypoglycemia in studies of healthy volunteers." (PMID 26021829, 2015). "With regard to monotherapy with OHAs, incidence of hypoglycemia was high in the patients using drugs to promote insulin secretion as 4% for SU agents and 3.8% for glinide agents, followed by 3.5% for pioglitazone, whereas ≤ 2% in patients using metformin, DPP-4 inhibitors, or α-GIs." (PMID 26566411, 2015). "Thus, our results suggest that reducing the insulin dose by up to 20% and discontinuing insulin secretagogues may prevent hypoglycemia when a DPP-4 inhibitor is added to insulin therapy." (PMID 25816296, 2015). "Importantly, both incretin analogues and DPP-4 inhibitors carry no risk of hypoglycemia; the benefit of the latter is that DPP-4 inhibitors can safely be given irrespective of renal function, including dialysis." (PMID 26398489, 2015). "In that study, the mean period of hypoglycemia after liraglutide administration was approximately 50 min/day and a higher frequency of hypoglycemia was observed after liraglutide injection than after administration of insulin or DPP-4 inhibitors such as vildagliptin and alogliptin." (PMID 25526642, 2014). "Dipeptidyl peptidase-4 (DPP-4) inhibitors have recently emerged as a new class of oral hypoglycemic agent and show favorable results in improving glycemic control (in particular postprandial hyperglycemic control) with low risk of hypoglycemia and weight gain, and overall good tolerability profile." (PMID 24883155, 2014). "The DPP-4 inhibitors promote glucose-dependent insulin secretion, i.e., in the presence of lower blood glucose values, the insulin release is not expected, which contributes to reduce the risk of hypoglycemia." (PMID 23697612, 2013).
Hypoglycemia (continued). "However, when combined with a sulfonylurea, mild to moderate hypoglycemia has been reported by up to 36% of patients treated with the combination of a GLP-1R agonist or a DPP-4 inhibitor, which necessitates reducing the dose of the sulfonylurea, usually by half." (PMID 22390369, 2012). "A thiazolidinedione or a dipeptidyl peptidase-4 (DPP-4) inhibitor may be considered as second-line options in place of a sulphonylurea if there is a significant risk of hypoglycaemia, or if a sulphonylurea is contraindicated or not tolerated." (PMID 21883438, 2012). "The lower risk of hypoglycaemia with sitagliptin relative to sulphonylureas overall is consistent with the glucose-dependent actions of DPP-4 inhibitors relative to the non-glucose-dependent mechanism of action of potassium channel-based insulin secretagogues, such as sulphonylureas." (PMID 21951832, 2011). "If glycemic control remains inadequate, changing the type of insulin or using medications like alpha-glucosidase inhibitors, DPP-4 inhibitors, and GLP-1RA can help lower blood glucose levels while preventing hypoglycemia." (PMID 39575003, 2024). "In the following years, new antihyperglycemic agents were gradually introduced in clinical practice, including the dipeptidyl-peptidase 4 (DPP-4) inhibitors, which have a safe profile in terms of hypoglycemia." (PMID 37700155, 2023). "DPP-4 inhibitors do not cause weight gain compared with the impact of a rapid decrease in blood glucagon, and because they act dependently on blood glucagon concentrations in the body, they have a low risk of hypoglycemia and are used as an adjuvant to dietary and exercise therapy." (PMID 37111730, 2023). "SGLT-2Is and dipeptidyl peptidase-4 inhibitors (DPP-4Is) do not cause hypoglycemia, are administered orally (The Royal Australian College of General Practitioners (RACGP), 2016), and may be preferred over sulfonylureas and insulin in people at high risk of hypoglycemia such as those who are frail." (PMID 35903329, 2022). "Although DPP-4 inhibitors are considered safe drugs, and unlikely to cause hypoglycemia, it has been reported that their use in combination with SU enhances the drug activity, mediated by the Epac2A/Rap1 signaling pathway, consequently leading to 50% rise in the risk of hypoglycemia." (PMID 30815039, 2019). "To date, there are few prospective randomized clinical trials that have compared the efficacy of SGLT2 inhibitors and DPP4 inhibitors regarding the prevention of CVD risks, such as hyperglycemia, body weight gain and severe hypoglycemia." (PMID 29895330, 2018). "With regard to the glycemic effectiveness of vildagliptin—a potent and selective DPP-4 inhibitor—with metformin, we found that this combination was effective for HbA1c reduction, was weight neutral, and did not present any additional risk of hypoglycemia in RCTs." (PMID 29057274, 2017). "After the launch of dipeptidyl peptidase-4 (DPP-4), a new oral hypoglycemic drug (OHD), in December 2009, severe hypoglycemia cases were reported in Japan." (PMID 24300302, 2012). "A low incidence of hypoglycemia is observed with the GLP-1R agonists and DPP-4 inhibitors, likely because of their glucose-dependent actions on insulin and glucagon secretion." (PMID 22390369, 2012). "Sitagliptin is an orally bioavailable selective DPP4 inhibitor that reduces blood glucose levels without significant increases in hypoglycemia." (PMID 40733260, 2025). "Interestingly, various studies have shown that DPP-4 inhibitors exhibit different effects depending on glucose levels: in hyperglycemia, DPP-4 inhibitors inhibit glucagon secretion, while in hypoglycemia, they enhance glucagon secretion." (PMID 39594662, 2024). "Various hypoglycemia-inducing drugs such as Metformin, glucagon-like peptide 1 (GLP-1) receptor agonists, dipeptidyl peptidase-4 (DPP-4) inhibitors, amylin analogs, and Sodium-Glucose Cotransporters 2 (SGLT-2) inhibitors, developed good outcomes in patients with T1DM." (PMID 38396657, 2024).